INS (insulin)
Diseases named in the same sentence as INS in open-access papers (continued):
Sharing a sentence is not in itself a finding about the gene and the disease.
Obesity (continued). "In our hands, a 26-week-long mangosteen extract supplementation led to glucose metabolism improvement in insulin resistant female subjects with obesity, with a frank decrease of HOMA-IR, independent of body weight change." (PMID 32962190, 2020). "Coherently, C57 mice showed reduced inflammation, and improved insulin signaling and glucose metabolism when given antibiotics while obesity-resistant 129S1 and obesity-prone 129S6 mice were not affected by antibiotics treatment." (PMID 31973214, 2020). "Although the minipigs in both FFC groups developed sever obesity and dyslipidemia, the insulin-signaling pathways were not affected." (PMID 32205840, 2020). "However, conditions such as obesity, T2DM, and pancreatic cancer result in an increase in the amount of amylin relative to the insulin, which can disturb the regulation of energy homeostasis." (PMID 32599958, 2020). "During obesity, increased production of insulin is required to maintain normal blood glucose levels." (PMID 32140136, 2020). "Here we provide a new piece of knowledge since our animals deficient in NOD1 and fed a HFD for 6 weeks, despite an evident obesity, are not resistant to insulin and exhibit an improved glucose tolerance test when compared with the WT counterparts." (PMID 32704052, 2020). "Obesity induced ER stress, represented by the increased pPERK signals suppressed tyrosine phosphorylation of IR and IRS, two markers of insulin signaling pathway." (PMID 32180905, 2020). "In a diet-induced obesity model, mice lacking March1 [March1 knockout (KO)] show increased insulin resistance compared to their WT counterparts." (PMID 32973799, 2020). "When obesity becomes chronic, insulin secretion eventually no longer compensates for increased insulin demands, resulting in hyperglycemia and T2D." (PMID 32140136, 2020). "Furthermore, in a genetic model of obesity, the UCP-DTA mouse, lipin 1 expression was decreased and lipin 1 overexpression improved insulin signaling and glucose tolerance." (PMID 33003344, 2020). "For example, two independent cross-sectional studies have demonstrated that activity levels and obesity (rather than aging) influence muscle insulin sensitivity, but ceramides were not measured." (PMID 32098447, 2020). "ET failed to improve the obesity and hyperglycemia, but improved insulin levels and prevented the hypocarnitinemia." (PMID 32365864, 2020). "Furthermore, the fasting insulin level showed a tendency to decrease, suggesting that PRE ameliorates obesity-induced glucose intolerance." (PMID 32183397, 2020). "Our results showed that the SFD consumption stimulatedthe development of metabolic syndrome regardless of sex:obesity, increased blood glucose, insulin, cholesterol levels,hepatic TG content, and decreased glucose tolerance and insulin sensitivity." (PMID 35087997, 2020). "The specific mechanisms by which obesity aggravates disease progression in MODY4 are not defined but elevated ER stress due to β-cell compensation in insulin-resistant states seems plausible." (PMID 31682591, 2020). "Further, corroborating the literature, we observed that obesity increased serum levels of proinflammatory cytokines TNF-α and IL-1β, and this improvement on inflammatory profile culminated in a lower hepatic sensitivity to insulin." (PMID 32847099, 2020). "Most published studies report inflammatory markers in single spot samples of obese and/or insulin dysregulated horses without documenting the duration of obesity and other relevant factors such as long-term ration formulation." (PMID 32321549, 2020). "Similar to obesity, adiponectin has a negative correlation to BMI in HF whilst leptin and insulin correlated positively with BMI." (PMID 33117276, 2020). "Regardless of obesity, HFDs contribute to glucose intolerance and insensitivity to the hypoglycemic effect of insulin." (PMID 33105762, 2020).
Obesity (continued). "Furthermore, chronic elevated serum levels of free fatty acids, seen in obesity and T2DM, induce lipotoxicity in beta-cells and suppress their insulin secretion ability." (PMID 32793223, 2020). "In the present study, we investigated whether an extract of Mori Cortex radicis affects p-IRS/PI3K/Akt insulin signaling and has neuro-protective effects in an HFD-induced mouse model of obesity." (PMID 32575897, 2020). "Hyperinsulinemia is well documented in individuals with obesity with or without IR and is related to increases in insulin secretion and decreases in insulin clearance rate." (PMID 31331009, 2019). "It has been demonstrated by studies that mouse models that have no, or are low in, hepatic lipid accumulation retained insulin sensitivity even if in time of obesity." (PMID 31427967, 2019). "We hypothesized that when given in conjunction with a HFS diet (diet-induced obesity (DIO) mouse model), CUR may prevent pancreatic islet changes and promote insulin signaling, ultimately regulating circulating insulin levels." (PMID 31372175, 2019). "To assess the metabolic consequences of maternal diet-induced obesity in the offspring, we first determined body weight gain and non-fasted insulin and leptin levels of the dams." (PMID 31572115, 2019). "Both obesity and DM2 are characterized by high serum free fatty acid (FFA) concentrations, reflecting an increased infiltration of macrophages in white adipose tissue (WAT) and lower insulin sensitivity." (PMID 30646503, 2019). "In patients with extreme obesity (BMI ~45 kg/m2), however, only an improvement in insulin secretion was observed with no changes in hepatic insulin sensitivity." (PMID 30918654, 2019). "Puberty is known to transiently reduce whole body insulin sensitivity by ~30%, regardless of the degree of obesity." (PMID 31474943, 2019). "Indeed, increased IL-6 levels in response to obesity or physical exercise promotes the secretion of the incretin hormone GLP-1 by intestinal L-cells and pancreatic α-cells leading to increased insulin secretion." (PMID 30989320, 2019). "From the results of the present study, we have concluded that exercise acts as a potential non-pharmacological aid that protects against obesity-induced decline in cognitive functions by improving hippocampal insulin signaling and neuroplasticity." (PMID 31311133, 2019). "FGF 19 transgenic mice did not develop obesity and DM on a high-fat diet by reducing fat mass, increasing energy expenditure, increasing insulin sensitivity, and reducing hepatosteatosis." (PMID 31181641, 2019). "The results in our study were consistent with recent findings that leptin, but not insulin, mediated the SNS-driven increase in heart rate and blood pressure associated with obesity." (PMID 31682617, 2019). "The present study provides evidence that in an experimental model of severe obesity, LECS reduced blood glucose and insulin levels, improved glucose tolerance and insulin sensitivity, and increased activity of hepatic transaminases without modification of body weight and food intake." (PMID 31636807, 2019). "Increasing evidence suggested a correlation among tyrosine levels, obesity, and insulin concentration in both diabetic and non-diabetic subjects." (PMID 31117294, 2019). "While activation of PPARγ restores insulin signaling, the impact of PPARγ in VSMCs in obesity-related pulmonary remodelling has not been determined in detail." (PMID 30813929, 2019). "Horses with obesity and EMS have significant dysfunction of the peri‐renal and retroperitoneal adipose tissue that may contribute to whole body insulin dysregulation." (PMID 30866087, 2019). "Our data demonstrated that blueberry-supplemented diet significantly increased insulin sensitivity in HFD-induced obesity mouse model, although the addition of blueberry did not prevent HFD-induced weight gain." (PMID 31139236, 2019).
Obesity (continued). "Deficiency of miR-146a did not influence obesity measured as HFD-induced body weight and fat mass gain, or metabolism of glucose and insulin tolerance." (PMID 31477775, 2019). "In patients with severe obesity (body mass index [BMI] ~30 kg/m2), an improvement in hepatic insulin sensitivity was quickly observed only after a week after VLCD, whereas beta cell defect in insulin secretion was restored later at 8 weeks." (PMID 30918654, 2019). "Having said that, a high BMI and severe obesity in childhood in an individual child do not necessarily confer the presence of very low insulin sensitivity." (PMID 31474943, 2019). "Thus, insulin and insulin-like growth factor type 1 (IGF-1) signaling pathways represent master regulators of pathophysiological processes directing obesity, DM, and cancer." (PMID 31847392, 2019). "Because MPC SkmKO mice showed a marked resistance to fat mass gains and increased insulin sensitivity on a normal chow diet, we sought to understand whether disrupting muscle MPC activity would attenuate high fat diet-induced obesity and metabolic dysfunction." (PMID 31305240, 2019). "High-fat diet-induced obesity increased liver lipid fraction and suppressed de novo lipogenesis but did not change fatty acid esterification and saturation or insulin sensitivity." (PMID 31341532, 2019). "However, mean fasting plasma insulin concentrations and HOMA-IR2 were significantly higher in the group with obesity than in the normal-weight group." (PMID 31877631, 2019). "Thus, as discussed in the section “Effect of ATGL on glucose homeostasis”, obesity-resistant ATGL knockout mice maintain glucose tolerant and insulin sensitive arguing against a metabolically “lipodystrophic” phenotype." (PMID 30367950, 2019). "When the population was classified by sexual development, both children (pre-pubertal stage) and adolescents (pubertal stage) with obesity showed higher body weight, height, BMI, waist circumference, HOMA index, and plasma insulin, and leptin than those with normal weight." (PMID 31207920, 2019). "In our study of a heterogeneous group of ambulatory subjects with and without obesity and metabolic dysfunction, some subjects showed an increase in total adiponectin and insulin sensitivity, and others showed the opposite." (PMID 31869355, 2019). "This study has shown that although insulin sensitivity was decreased after major surgery in both obese and non-obese subjects, preoperative carbohydrate treatment or obesity did not have an impact on the magnitude of change." (PMID 29454501, 2019). "Despite having obesity, individuals with MHO display a “favorable” metabolic profile, with preserved insulin sensitivity, normal blood pressure and glucose regulation, normal lipids and liver enzymes, as well as a normal hormonal, inflammation, and immune profile." (PMID 31920976, 2019). "Speed eating causes an increase in the total amount of energy while ingesting foods, lack of feeling of fullness, and insulin resistance, which finally leads to obesity." (PMID 31261847, 2019). "Major abdominal surgery was associated with a 42% reduction in insulin sensitivity from mean(SD) M value of 37.3(11.8) μmol kg−1 fat free mass (FFM) to 21.7(7.4) μmol kg−1 FFM, but this was not influenced by obesity or preoperative carbohydrate treatment." (PMID 29454501, 2019). "The investigated transgenic mouse model shows a mild fatty liver, hepatic insulin resistance with compensatory increased ß-cell function, and massive obesity but no signs of inflammation and metabolically healthy adipose tissue." (PMID 31709254, 2019). "Indeed, based on these postulates, low adiponectin levels characterising women with obesity and GDM would remove the inhibition of this adipokine on placental insulin signalling and amino acid transport, thereby promoting increased foetal growth." (PMID 30934676, 2019).
Obesity (continued). "The exercise intervention for obesity rat could reduce the inflammatory markers in all adipose tissue, and improve the BAT mitochondrial function, insulin resistance, and the relative abundance of Streptococcaceae." (PMID 31620020, 2019). "It is also a potent insulin sensitizer with a negative correlation with obesity, T2DM, MetS, and cardiovascular diseases." (PMID 31969813, 2019). "Together, these findings provide insight into the metabolic abnormalities that occur across the continuum of insulin responses through the spectrum of normoglycaemia and prediabetes independent of obesity." (PMID 31489455, 2019). "However, the fasting blood glucose, fasting insulin and HOMA-IR in T2DM with obesity who supplemented RS were lower than control group, and the subgroup analysis according to the dose of RS supplementation was inconsistency." (PMID 31760943, 2019). "In both the OSA with and without EDS groups, MetS was mainly represented by insulin resistance [model 2: loading = 0.93, p < 0.001; model 3: loading = 0.88, p < 0.001] and obesity [model 2: loading = 0.91, p < 0.001; model 3: loading = 0.89, p < 0.001]." (PMID 31801522, 2019). "Other limitations include the small sample size, the lack of reporting of other variables known to affect energy metabolism and appetite such as ghrelin and insulin hormone levels, and the non-utilization of waist circumference as a marker for obesity." (PMID 31557979, 2019). "Nonetheless, the direct delivery of insulin in the brain did not reverse the obesity-induced metabolic disorders suggesting that the defect in insulin uptake into the brain is not the only mechanism." (PMID 30906281, 2019). "A recent study identified several plasma metabolites predicting changes in insulin sensitivity in obese, nondiabetic subjects from the Diet, Obesity, and Genes (DiOGenes) Study10." (PMID 31554919, 2019). "TNF is upregulated in the presence of obesity and impacts the expression of other multiple inflammatory factors such as IL-6 and LCN2 that promote, exacerbate, and sustain chronic systemic inflammation and insulin impairment." (PMID 31892368, 2019). "Irrespective of obesity, skeletal muscle can also lose insulin sensitivity as a consequence of kidney failure." (PMID 31195596, 2019). "We analyzed the relationship between obesity and inflammation in obese and nonobese groups according to both insulin levels and IR." (PMID 30761879, 2019). "Interestingly, neuron-specific deletion of PTP-1B in mice enhanced hypothalamic insulin sensitivity and prevents HFD-induced obesity and related metabolic dysfunctions." (PMID 30906281, 2019). "One report postulated that SDF-1 may serve to desensitize adipocytes to insulin and another suggested that SDF-1 modulates angiogenesis in obesity." (PMID 30909581, 2019). "On the other hand, the plasma Hcy level did correlate neither with obesity parameters nor with those respecting insulin resistance." (PMID 31321096, 2019). "That the group with obesity, which is more insulin resistant, suppressed EGP more than the group with normal weight, which is more insulin sensitive, may sound paradoxical." (PMID 31877631, 2019). "The health-enhancing PA group was older and had fewer cardiovascular risk factors, including lower BMI, LDL-C, triglycerides, and blood insulin levels, higher HDL-C, a lower prevalence of obesity and fatty liver, and less alcohol intake than those with insufficient PA." (PMID 30862894, 2019). "In mice, it has been shown that the treatment with recombinant THBS1 may suppress insulin signaling in the cultured muscle cell, which could represent crosstalk between the WAT and skeletal muscle in obesity." (PMID 31581657, 2019). "In turn, the observed hyperinsulinemia after consuming the glucose drink in the group with obesity might explain the remarkable difference in EGP between groups, because EGP is very sensitive to small increases in circulating insulin." (PMID 31877631, 2019).
Obesity (continued). "Nevertheless, in this obesity model, no changes were observed in basal glucose, insulin or alterations of the lipid profile." (PMID 30949067, 2019). "Obesity, accompanied by increases in basal insulin and leptin, decreases rather than increases spontaneous energy expenditure through physical activity." (PMID 30678194, 2019). "A further understanding of leptin and insulin signaling within the hypothalamic ARC and the contribution of epigenetic mechanisms to the onset of obesity and related complications could aid in the development of novel antiobesity strategies." (PMID 31660128, 2019). "Activation of hippocampal insulin signaling by exercise might increase hippocampal neuroplasticity including BDNF and neurogenesis in the presence of obesity." (PMID 31311133, 2019). "Among the numerous adipokines, adiponectin is regarded as unique and salutary, showing negative correlations with several age- and obesity-related metabolic disturbances and a positive correlation with longevity and insulin sensitivity among centenarians." (PMID 30923512, 2019). "In addition, obesity and high-fat diet (HFD) feeding also promote lipolysis and decrease lipogenesis, in turn, perturbing cellular insulin signaling." (PMID 31208033, 2019). "Although not significant using multiple comparison testing, aging and obesity appeared to adversely influence nonfasted blood insulin levels." (PMID 31111669, 2019). "Our study demonstrates for the first time that CT-1 levels in the scFEM but not the scABD, were negatively associated with visceral adiposity and intrahepatic lipid, while positively correlated with insulin sensitivity, as assessed by the Matsuda Index and HOMA-IR, in women with obesity." (PMID 31013924, 2019). "In obesity and T2D, peripheral WAT develops IR and exhibits impaired insulin signaling." (PMID 30800100, 2019). "The obesity epidemic might affect patients with type 1 diabetes (T1DM), historically described as lean and insulin-sensitive subjects." (PMID 30617710, 2019). "One study using direct addition of acetate and propionate to diets with low or high fat inclusion demonstrated that SCFAs improved hepatic lipid metabolism and insulin sensitivity independent of overall obesity phenotype." (PMID 31208043, 2019). "We do not have data about the effects of maqui on normal chow-fed animals where neither obesity nor insulin resistant is present, but this experimental approach will be included in our further studies." (PMID 31480627, 2019). "It is therefore a "fuel repartitioning effect", leading to a redistribution of metabolic fluxes, that can explain why resveratrol is useful for anti-obesity and anti-diabetic approaches in rodents, rather than being a simple and deleterious anti-insulin agent." (PMID 30917543, 2019). "Taken together, FMT in patients with obesity and MS showed a short-term benefit on insulin sensitivity but did not confer a benefit with regards to other clinical parameters." (PMID 31557953, 2019). "As only male offspring exposed to maternal obesity during lactation demonstrated an altered glucose tolerance, measurements of insulin signalling mRNA expression focused on male rather than female tissues." (PMID 31300679, 2019). "In a study of 40 treatment-naïve, nondiabetic German subjects, insulin sensitivity as assessed by a hyperinsulinemic euglycemic clamp was not significantly improved in patients with obesity." (PMID 30426019, 2018). "Hepatic Ago1 is dispensable for obesity-induced pathophysiology, as deletion of hepatic Ago1 did not affect diet-induced weight gain, glucose tolerance, or insulin sensitivity." (PMID 30201950, 2018). "In wild type (WT) and PKR-/- mice, blood glucose, insulin and lipid levels and the brain expression of the phosphorylated components of the metaflammasome—PKR, JNK, IRS1 and IKKbeta—were studied after the induction of obesity by a high fat diet (HFD)." (PMID 29795582, 2018).